EIF3A (eukaryotic translation initiation factor 3 subunit A)
Diseases named in the same sentence as EIF3A in open-access papers (continued):
Sharing a sentence is not in itself a finding about the gene and the disease.
colon carcinoma (11 papers, 2009 to 2025). "Correlation analysis revealed a significant positive association between eIF3a and eIF3i overexpression in human colon cancers." (PMID 39413959, 2024). "An association of eIF3a overexpression with poor clinical prognosis was reported recently in colon cancer patients following surgery." (PMID 22619676, 2012). "Based on above findings, we hypothesized that APC mutations in human colon cancer tissues would upregulate the expression of eIF3a." (PMID 39413959, 2024). "However, over-expressing the wild-type APC gene drastically reduced eIF3a expression at both protein and mRNA levels in human colon cancer HT29 and CaCo-2 cells, which are known to have mutated APC gene." (PMID 39413959, 2024). "A close association with eIF3A could indicate a coupling to protein folding, in particular proline-isomerization and translation in the colon carcinoma cell line." (PMID 33799492, 2021). "Thus, it is likely that APC mutation causes eIF3a upregulation in human colon cancer." (PMID 39413959, 2024). "Thus, we conclude that eIF3a plays an important role in intestinal/colon tumorigenesis and inhibiting eIF3a may intercept APC mutation-induced colon tumor production." (PMID 39413959, 2024). "The technique has already been applied to the eIF3a protein, as a virally expressed form of eIF3a-BirA* was used to identify the interactome in colon cancer cells." (PMID 41423661, 2025). "We show that eIF3a expression is upregulated in human colon cancer tissues, pre-cancerous adenoma polyps, and associates with β-catenin level and APC mutation in human samples, and that eIF3a overexpression transforms intestinal epithelial cells." (PMID 39413959, 2024). "We also designed experimental validations for RPA2-RPA3 and for EIF3A-EIF3E, but knocking down RPA2 or EIF3A proved to be lethal for the transfected HCT116 colon cancer cell lines." (PMID 29032074, 2017). "In vitro assays of colon cancer cell lines indicated a similar dependence on decreased eIF3a expression for differentiation of cells." (PMID 22619676, 2012). "Future studies are necessary to characterize eIF3a as a drug target for colon cancers." (PMID 39413959, 2024). "Of the eIF3(a:b:i:g) subcomplex, eIF3i has been shown to overexpress in human colon cancers." (PMID 39413959, 2024). "The finding that the increased expression of eIF3a and eIF3i strongly associates with each other in 19 of the 22 matched pairs of human tissues is consistent with the conclusion that both eIF3a and eIF3i may be regulated similarly in colon cancers." (PMID 39413959, 2024). "We applied the BioID technique to two rapidly dividing cell lines (the immortalized embryonic cell line HEK-293T and the colon carcinoma cell line HCT-166) in order to identify interacting proteins of eIF3A, a core subunit of the eukaryotic initiation factor 3 complex." (PMID 33799492, 2021). "Recent studies have revealed that eIF3a expression is elevated in several cancer cell lines, while a comparison of the expression levels in human ovary, kidney, lung, breast and colon cancer tissue to normal tissue showed specific high eIF3a expression in lung cancer." (PMID 28074905, 2017). "In a previous study, we could show in colon cancer that high eIF3a expression correlates with poor prognosis." (PMID 22619676, 2012). "Together, we conclude that eIF3a upregulation in colon cancer is due to APC mutation and it participates in colon tumorigenesis by adding a translational control axis in the Wnt/β-catenin signaling pathway and that it can serve as a potential target for colon cancer intervention." (PMID 39413959, 2024). "Thus, the Wnt/β-catenin pathway, like the mTOR pathway, contains a translational control axis mediated by eIF3a, which could serve as a novel therapeutic target in colon cancer." (PMID 39413959, 2024). "Thus, eIF3a and eIF3i in the eIF3(a:b:i:g) subcomplex may be related to colon cancer and are up-regulated together prior to the formation of malignant colon tumors." (PMID 39413959, 2024).
colon carcinoma (continued). "While the association analyses using these datasets from different experiments have limitations, the fact that they were from the same samples and showed strong correlation suggests that Wnt/β-catenin signaling may contribute to the upregulation of both eIF3a and eIF3i in human colon cancers." (PMID 39413959, 2024). "The other cell line, the colon carcinoma line HCT-116, has been reported to contain an amplified eIF3A gene, which is why it exhibits an increased abundance of eIF3A mRNA." (PMID 33799492, 2021). "As subunits in the eIF3(a:b:i:g) subcomplex, only eIF3a and eIF3i, but not eIF3b and eIF3g, are overexpressed in human colon cancers compared with their matching normal tissues." (PMID 39413959, 2024). "In addition, eIF3a was also found to be elevated in a number of other cancers, including squamous cell carcinoma of the oral cavity (OSCC), lung, cervix, esophagus, stomach and colon cancers." (PMID 26213845, 2015).
hepatocellular carcinoma (11 papers, 2016 to 2026). A malignant tumor that arises from hepatocytes. "Recent reports suggested that eIF3a could mediate glycolytic metabolism, and the level of anti-eIF3A autoantibody in serum may represent a potential diagnostic marker for hepatocellular carcinoma." (PMID 34512348, 2021). "Recent investigations have implicated that eIF3a was upregulated in several solid tumors, such as urinary bladder cancer (UBC) and hepatocellular carcinoma (HCC), eIF3a expression has been found to be associated with prognosis of tumor patients." (PMID 38589831, 2024). "For example, EIF3A can promote the glycolysis in hepatocellular carcinoma by regulating the hypoxia-inducible factor 1-alpha." (PMID 36051357, 2022). "Therefore, it was concluded that eIF3a might be a potential therapeutic target for hepatic carcinoma (HCC) since it acts as a regulator for glycolysis—a process that is central to cancerous reprogramming of metabolism." (PMID 32961898, 2020). "miR-875-5p is down-regulated in hepatocellular carcinoma, and it inhibits tumor growth and metastasis by targeting the 3’UTR of eIF3a to down-regulate its expression." (PMID 38275418, 2024). "Exosomes enriched by differential ultracentrifugation of hepatoma cell-cultured media (HepG2 and Hepa-1c1c7) were analyzed by Western blotting and was stained with XC90 or anti-EIF3A antibody." (PMID 31363116, 2019). "In addition, the translation facilitated by METTL16, which is important in the carcinogenesis of hepatocellular carcinoma, is mediated by the interaction between METTL16 and EIF3A and EIF3B." (PMID 36051357, 2022).
glioma (9 papers, 2017 to 2024). A benign or malignant brain and spinal cord tumor that arises from glial cells (astrocytes, oligodendrocytes, ependymal cells). "By contrast, the expression of eIF3a and eIF3l was decreased in higher grade gliomas and was associated with better overall survival (Both HR < 1 and P < 0.05)." (PMID 31171919, 2019). "Unexpectedly, FMR1, EIF3A, and ZC3H13, whose high expressions indicated poor prognosis, were up-regulated in the IDH mutant and 1p19q codeletion gliomas since the two genomic mutations indicated favorable prognoses." (PMID 33240891, 2020). "The results indicated that the expression levels of eIF3a, eIF3b, eIF3i, eIF3k, eIF3l and eIF3m were significantly (P < 0.05) correlated to the OS of glioma patients in both datasets." (PMID 31171919, 2019). "Especially, EIF3A is found to be overexpressed in some glioma patients." (PMID 28198665, 2017). "Among these eIF3 subunits, the expression of eIF3a was negatively correlated with the WHO grade of gliomas, especially in the TCGA dataset." (PMID 31171919, 2019).
colorectal cancer (8 papers, 2019 to 2026). A primary or metastatic malignant neoplasm that affects the colon or rectum. "We performed western blot assay to test PPP2R5A expression in control and eIF3a‐knockdown colorectal cancer cells." (PMID 35187743, 2022). "This study comprehensively investigated the role and mechanism of eIF3a in tumor invasion and metastasis in colorectal cancer." (PMID 35300416, 2022). "To determine the potential function of eIF3a in colorectal cancer, we first analyzed the effect of eIF3a expression on the overall survival of colorectal patients in The Cancer Genome Atlas (TCGA) datasets." (PMID 35300416, 2022). "Given the proto-oncogenic role of eIF3a in several other types of tumors, we investigated the specific features of eIF3a in colorectal cancer." (PMID 35300416, 2022). "In consideration of the potential accelerative effect of eIF3a in the metastasis of colorectal cancer patients indicated before, the biological functions of eIF3a on malignant cell metastasis were investigated." (PMID 35300416, 2022). "We depleted eIF3a in colorectal cancer cells and then performed cell wound healing and Transwell migration assays." (PMID 35300416, 2022). "In conclusion, eIF3a plays a vital role in colorectal cancer cell proliferation and viability, which also partly explains the aberrant expression of eIF3a in colorectal tumor samples." (PMID 35300416, 2022). "This study demonstrated for the first time that eIF3a negatively regulates irinotecan sensitivity in colorectal cancer." (PMID 35187743, 2022). "We found that eIF3a is selectively overexpressed in tumor tissues and positively correlated with the metastatic phenotype and poor prognosis in colorectal cancer patients." (PMID 35300416, 2022). "Taken together, these results demonstrated that eIF3a contributes to colorectal cancer cell metastasis and motility in vitro." (PMID 35300416, 2022). "Our results support the conclusion that eIF3a is a potential biomarker for colorectal cancer progression and metastasis." (PMID 35300416, 2022). "Here, we applied the BioID proximity-based biotin labeling technique to identify interacting proteins of eIF3A in two human cell lines: the human colorectal carcinoma cell line HCT-116 and the human embryonic kidney cell line HEK-293T." (PMID 33799492, 2021). "Our study identified eIF3a as a promising target for inhibiting colorectal cancer metastasis." (PMID 35300416, 2022). "eIF3a exhibits oncogenic behavior in several types of cancer; however, its role in colorectal cancer remains unclear." (PMID 35300416, 2022). "To summarize, eIF3a significantly affects irinotecan‐induced colorectal cancer cell apoptosis." (PMID 35187743, 2022). "This study characterized the role of eIF3a in colorectal cancer metastasis." (PMID 35300416, 2022). "Furthermore, knockdown of eIF3a in colorectal cancer cell lines significantly impaired cellular proliferation, and both findings were verified in vitro and in vivo." (PMID 35300416, 2022). "EIF3A, the largest subunit of eIF3, has been reported to be highly expressed in malignant tumors, and its abundance correlates with dedifferentiation, continuously increasing from normal mucosa via hyperplastic to neoplastic transformation in colorectal cancer." (PMID 33799492, 2021). "Recent studies have shown that eIF3a was highly expressed in esophageal squamous cell carcinoma (ESCC), colorectal cancer and thyroid cancer (TC), but lower in clear cell renal cell carcinoma (ccRCC)." (PMID 38589831, 2024). "To exclude the possible effect of proliferation inhibition on irinotecan sensitivity, we selected a colorectal cancer cell line, SW620, which showed least sensitive to eIF3a‐knockdown‐induced proliferation inhibition." (PMID 35187743, 2022).
gastric cancer (8 papers, 2012 to 2024). A primary or metastatic malignant neoplasm involving the stomach. "eIF3a (p150) is overexpressed in gastric cancer, and its expression is associated with the clinicopathological parameters of gastric cancer." (PMID 31423012, 2019). "Most notably, increased levels of the largest eIF3 subunit, eIF3a, have been found in breast, cervix, esophagus, lung, and stomach cancers." (PMID 28083147, 2016). "For example, high levels of EIF3a have been reported in breast, cervix, esophagus, lung and stomach cancers." (PMID 27340783, 2016). "Overexpression of EIF3A occurs in many solid tumors and cancer cell lines including human breast, cervical, esophageal, lung, gastric cancers and Hela cells." (PMID 23226446, 2012). "Multiple components of the EIF3 are now known to be dysregulated in multiple cancers (EIF3A in breast, cervical, lung and gastric cancers; EIF3B in breast and gastric cancers; EIF3C in testicular cancers; and EIF3H in prostate cancers)." (PMID 35528200, 2022).
non-small cell lung carcinoma (8 papers, 2003 to 2024). A group of at least three distinct histological types of lung cancer, including non-small cell squamous cell carcinoma, adenocarcinoma, and large cell carcinoma. "eIF3a sustains non-small-cell lung cancer stem cell-like properties by promoting the YY1-mediated transcriptional activation of β-catenin." (PMID 38275418, 2024). "Our previous study further identified that eIF3a also contributed to non-small cell lung cancer (NSCLC) patients' response to platinum-based chemotherapy by regulating the expression of some DNA repair proteins." (PMID 26213845, 2015). "Over-expressed eukaryotic initiation factor 3a (eIF3a) in non-small cell lung cancer (NSCLC) contributed to cisplatin sensitivity." (PMID 24789280, 2014). "Some studies have shown that some genes and their generated circRNA have similar biological functions, so we speculated that circRNA derived from the eIF3a gene may also have similar biological functions with to parent gene in non-small-cell lung cancer." (PMID 38275418, 2024).
pancreatic cancer (7 papers, 2021 to 2024). "In pancreatic cancer, overexpression of pseudogene Wilms tumor 1-associated protein pseudogene 1 (WTAPP1) enhances the recruitment of more translation initiation factor–eukaryotic translation initiation factor 3 (EIF3) complex (EIF3A to EIF3M) by EIF3B and promotes WTAP translation." (PMID 36139062, 2022). "Furthermore, pancreatic cancer patients with lower METTL3, METTL14, RBMX, FTO, ALKBH5, YTHDF1, and YTHDC1 mRNA expression levels or higher VIRMA, HNRNPA2B1, EIF3A, IGF2BP1, IGF2BP2, and IGF2BP3 mRNA expression levels had significantly poorer OS (P < 0.05)." (PMID 34330301, 2021).
bladder cancer (6 papers, 2016 to 2024). "EIF3a is overexpressed in urinary bladder cancer, and high EIF3a expression was linked to longer overall survival rates of patients with low-grade tumors." (PMID 36686818, 2022).
viral infection (6 papers, 2019 to 2025). "The expression of eIF3a varies with exposure to thermal stress, hypoxia stress, irradiation stress, nutrient starvation stress, and viral infections." (PMID 37152897, 2023). "In addition, eIF3a was involved in cell cycle arrest, cell apoptosis, cell proliferation, embryo development, virus infection, promotion of tumor initiation and development, and chemotherapy and radiation therapy of cancers." (PMID 37152897, 2023). "Other factors which can influence to induce autoantibodies, such as gender, age, or viral infection do not seem to affect the anti-EIF3A autoantibody response significantly." (PMID 31363116, 2019).
esophageal cancer (4 papers, 2013 to 2025). A primary or metastatic malignant neoplasm involving the esophagus. "Cellular experiments demonstrated ROBO1 directly interacted with eukaryotic translation initiation factor 3A (eIF3A) and accelerated its degradation in esophageal cancer cells after irradiation treatment." (PMID 40188129, 2025). "Furthermore, another two studies also demonstrated that high eIF3a level had better survival than that with low eIF3a expression in cervical and esophageal cancer patients." (PMID 26213845, 2015). "However, it has been observed previously that cervical and esophageal cancer patients with high eIF3a level had better relapse-free and overall survival than those with low eIF3a expression." (PMID 24386425, 2013).
lung adenocarcinoma (4 papers, 2013 to 2022). A carcinoma that arises from the lung and is characterized by the presence of malignant glandular epithelial cells. "Accordingly, we found lower eIF3a expression in the A549/DDP cell line (a drug resistant lung adenocarcinoma cell line) compared with parental A549 cells." (PMID 28074905, 2017).
melanoma (4 papers, 2019 to 2025). A malignant, usually aggressive tumor composed of atypical, neoplastic melanocytes. "EIF3A expression has also been previously linked to chemotherapeutic sensitivity in both melanoma and lung cancer." (PMID 38693155, 2024). "We found that eIF3a was downregulated in vemurafenib-resistant A375 cells, and its depletion significantly decreased the response of melanoma cells to BRAF inhibitors." (PMID 34512348, 2021). "The results showed that the expression of eIF3a was positively correlated with PPP2R1B expression in patients with melanoma." (PMID 34512348, 2021). "These experiments confirmed the involvement of eIF3a in regulating the sensitivity of human melanoma cells to dabrafenib." (PMID 34512348, 2021). "eIF3a was expressed at significantly lower levels in vemurafenib-resistant A375 melanoma cells (A375R) than in parental A375 cells." (PMID 34512348, 2021). "Moreover, our findings highlight eIF3a as a promising biomarker for melanoma or other cancers to predict the therapeutic effect of vemurafenib." (PMID 34512348, 2021). "Here, this study reported for the first time that eIF3a expression is positively correlated with vemurafenib sensitivity in melanoma cells, and this effect of eIF3a is mediated by regulating the translation of the protein phosphatase PPP2R1B, which inhibits ERK phosphorylation." (PMID 34512348, 2021). "Furthermore, siRNA-mediated knockdown of eIF3a decreased the responses of human melanoma cells to vemurafenib, as evidenced by the results of the CCK8 assay and colony formation assay." (PMID 34512348, 2021). "The positive relationship between eIF3a and PPP2R1B expression was also observed in melanoma tissues." (PMID 34512348, 2021). "In addition, consistent with other phosphatases of ERK, PPP2R1B knockdown in melanoma cell lines led to increased ERK phosphorylation and mediated the negative regulatory effect of eIF3a on vemurafenib sensitivity." (PMID 34512348, 2021). "Furthermore, eIF3a controlled ERK activity by regulating the expression of the phosphatase PPP2R1B via a translation mechanism, thus determining the sensitivity of melanoma cells to vemurafenib." (PMID 34512348, 2021). "In addition, we also evaluated the effect of eIF3a on the antitumor activity of dabrafenib, another BRAF inhibitor approved by the FDA to treat melanoma." (PMID 34512348, 2021).
prostate carcinoma (4 papers, 2013 to 2025). A carcinoma that arises from epithelial cells of the prostate gland. "The expressions of two m6A-RMRs such as EIF3A and RBMX were upregulated in prostate carcinoma samples compared with normal prostate epithelium-adjacent samples." (PMID 35211628, 2022).
oral squamous cell carcinoma (3 papers, 2012 to 2024). "In patients with ESCC, ccRCC, low-grade UBC and oral squamous cell carcinoma (OSCC), high levels of eIF3a were associated with favorable prognosis." (PMID 38589831, 2024).